BRCA2 (BRCA2 DNA repair associated)
Diseases named in the same sentence as BRCA2 in open-access papers (continued):
Sharing a sentence is not in itself a finding about the gene and the disease.
breast cancer (continued). "A noncoding polymorphism at 5′UTR in RAD51 has been shown by multiple independent studies to increase breast cancer risk in BRCA2 carriers." (PMID 32255263, 2020). "Mutations in the genes BRCA1 and BRCA2 represent a significant risk factor for ovarian and breast cancer." (PMID 32719921, 2020). "Mutations in BRCA1 and BRCA2 genes represent a significant independent risk factor for ovarian and breast cancer." (PMID 32719921, 2020). "BRCA1 and BRCA2 act as tumor suppressor proteins, and patients with inherited mutations therein are more likely to develop aggressive breast cancers." (PMID 32824813, 2020). "RAD52 S346X was highly significantly associated with reduced risk of breast cancer for BRCA2 carriers; each copy of the minor allele was estimated to confer a per‐allele HR of 0.69 (95% CI, 0.56 to 0.86, P = 0.0008)." (PMID 32175645, 2020). "Women with pathogenic germline gene variants in BRCA1 and/or BRCA2 are at increased risk of developing ovarian and breast cancer." (PMID 32165993, 2020). "In the general population, it is only a small proportion of breast cancer patients who actually exhibit rare mutations in certain genes, such as BRCA1 and BRCA2 genes, that confer the highest risks of developing breast cancer." (PMID 32823908, 2020). "The variant c.8331 + 1 G > A in BRCA2 was reported as likely pathogenic as a risk for breast cancer, in a boy presenting with thrombocytopenia." (PMID 31937788, 2020). "Prior studies have illustrated that mutation in BRCA2 would increase the risk of breast cancer, ovarian carcinoma, prostate cancer and other tumors." (PMID 32571290, 2020). "Activation of epithelial-mesenchymal transition in a mouse model of BRCA2-deficient breast cancer has also been found to trigger olaparib resistance." (PMID 32526907, 2020). "In patients with advanced breast cancer associated with BRCA1 or BRCA2 mutations, olaparib and talazoparib are now approved for treatment." (PMID 32733560, 2020). "In fact, it is estimated that BRCA2 mutants carry a 50%–60% lifetime risk of developing breast cancer." (PMID 32638521, 2020). "Previous studies reported that 4–40% and 0–11% of patients with male breast cancer harbored BRCA2 and BRCA1 mutations, respectively." (PMID 33054725, 2020). "Remarkably, minigenes of the splicing vector pSAD have been successfully used to assay more than 300 variants of the breast cancer gene BRCA2." (PMID 32211025, 2020). "In this study, we have successfully identified a germline mutation in the BRCA2 gene in a large Chinese family with breast cancer, expanding the knowledge and information about genetic mutations related to breast cancer." (PMID 31782247, 2020). "Intensive combined breast cancer screening with annual MRI and mammography has been shown to improve survival rates for BRCA2 mutation carriers." (PMID 31734900, 2020). "Only 5–10% of breast cancer cases are attributed to inherited mutations (BRCA1, BRCA2, and other breast cancer susceptibility genes)." (PMID 32118013, 2020). "This study population consisted of 608 breast cancer patients with a pathogenic BRCA2 variant, diagnosed between 1975 and 2018." (PMID 32939053, 2020). "For pathogenic BRCA2 carriers, the respective risks are 41–70% for breast cancer and 7.5–34% for ovarian cancer." (PMID 33081408, 2020). "Hereditary and genetic factors, including a personal or family history of breast or ovarian cancer as well as inherited mutations (in BRCA1, BRCA2, and other breast cancer susceptibility genes) account for 5% to 10% of breast cancer cases." (PMID 32471217, 2020). "In conclusion, in this work we described a novel BRCA2 splice variant identified in a 33‐year‐old breast cancer patient belonging to a HBOC family." (PMID 33159495, 2020). "It has been well-reported in previous studies that positive carriers for BRCA1/BRCA2 have high cumulative risk estimates for developing breast cancer reaching 72% for BRCA1 carriers and 69% for BRCA2 carrier by age of 805." (PMID 33067490, 2020).
breast cancer (continued). "Cancer predisposition genes, BRCA1 and BRCA2, were first discovered in the genetic study on familial breast cancer." (PMID 32269964, 2020). "Is the wildtype BRCA2 gene associated with good (living disease-free) breast cancer clinical outcomes?" (PMID 33391340, 2020). "BRCA1 and BRCA2 carrier tumors have characteristic mutation profiles, accompanied by homologous recombination deficiency, which distinguishes these from unselected breast carcinomas on a molecular level." (PMID 32964118, 2020). "In comparison with BRCA1-mutated cancer, BRCA2-mutated breast carcinomas frequently express ER and PGR; additionally, HER2 is expressed at the same frequency." (PMID 32269964, 2020). "In a recent study, a truncating variant of RAD52 has been found to significantly reduce the breast cancer risk in BRCA2 mutation carriers, which supports a role for RAD52 as a genetic modifier of cancer predisposition associated with BRCA2 loss." (PMID 32255263, 2020). "Deleterious germline PV carriers in BRCA1 or BRCA2 have an elevated lifetime risk of developing breast and/or ovarian cancer, particularly 60–80% for breast cancer (BC) and 26–54% for BRCA1 and 10–23% for BRCA2 for ovarian cancer (OC)." (PMID 32438681, 2020). "In less than 5% of cases, breast cancers (BC) are associated with germline mutations in breast cancer 1 (BRCA1) or breast cancer 2 (BRCA2) (gBRCA1/2m) genes." (PMID 32471249, 2020). "Out of 10 other human breast cancer genes, BRCA2 (and BRCA1) stood out as contributing to the risk of canine mammary tumors in the English springer spaniel." (PMID 32005245, 2020). "Inherited mutations in BRCA1 and BRCA2 are associated with increased risk to breast cancer and are enriched in patients with an early age of diagnosis and family history of breast and ovarian cancer." (PMID 31022191, 2019). "We prospectively evaluated the relationship between plasma RANKL and breast cancer risk among women with a BRCA1 or BRCA2 mutation." (PMID 31069010, 2019). "The Hereditary Breast and Ovarian Cancer (HBOC) syndrome is caused by loss-of-function mutations in the BRCA1 and BRCA2 genes and explains approximately 16% of inherited breast cancers." (PMID 30781715, 2019). "Women with an inherited mutation in BRCA1 or BRCA2 experience similar frequency, severity, and timing of hematologic toxicities during curative intent breast cancer chemotherapy as matched wild‐type patients." (PMID 31407530, 2019). "The proportion of PTEN mutant samples in BRCA-proficient, and in BRCA1- and BRCA2-deficient breast cancers was 7.9%, 29%, and 5.9%, respectively." (PMID 31022191, 2019). "BRCA1 and BRCA2 are tumor suppressor genes typically mutated in breast cancer and highly connected with cancer aggressiveness and survival." (PMID 32010625, 2019). "Women who inherit a deleterious mutation in BRCA1 or BRCA2 are at increased risk of developing breast cancer." (PMID 31407530, 2019). "Over the last two decades since the discovery of the first high-risk breast cancer susceptibility genes breast cancer 1 (BRCA1) and BRCA2, an extensive body of literature has grown regarding the causes of hereditary and familial breast cancer." (PMID 30823486, 2019). "In our case, the patient's son had a past history of breast cancer and both patients desired genomic sequencing analysis, which revealed a shared BRCA2 mutation at p.E2877*." (PMID 31631483, 2019). "Despite being driven by germline mutations in functionally related genes,BRCA1, BRCA2, and PALB2mutated breast cancers constitute a heterogeneous group of tumors at theimmunohistochemical and molecular level." (PMID 31067289, 2019).
breast cancer (continued). "He had a 51‐year‐old son with breast cancer history sharing the same mutation, implying that BRCA2 mutations are associated with elevated cancer risk among Japanese males." (PMID 31631483, 2019). "This case presents with an unusual subtype and difficult histologic diagnosis of a synchronic medullar breast cancer and ovary carcinoma associated with a new mutation of the BRCA2 gene." (PMID 30723561, 2019). "The patient's son had been diagnosed with breast cancer 2.5 years ago and was found to have the same germline BRCA2 mutation." (PMID 31631483, 2019). "After controlling for pathologic features and cancer treatments, positive ER status was the strongest predictor of mortality in this cohort of women with BRCA2-associated breast cancer (HR = 2.08; 95% CI 0.99–4.36, p = 0.05)." (PMID 30723304, 2019). "This is the first report of a novel BRCA2 pathogenic variant in a Senegalese family with hereditary breast cancer." (PMID 31060517, 2019). "Monoallelic variants and a heterozygous state are proven to be associated with a high risk for breast cancer development, almost comparable to that of BRCA2." (PMID 31312277, 2019). "BRCA1 and BRCA2 have been described as “breast cancer susceptibility genes,” so failure to properly repair mutations in these genes increases the risk for breast cancer." (PMID 31715586, 2019). "In conclusion, our results show that some challenges exist in the early detection of breast cancers in BRCA1 or BRCA2 mutation carriers." (PMID 30980249, 2019). "The tumors which had been imaged by both mammography and MR were divided into 30 breast cancers in BRCA1 mutation carriers and 29 breast cancers in BRCA2 mutation carriers." (PMID 30820924, 2019). "We aimed to investigate the expression level of breast cancer susceptibility gene 2 (BRCA2) and its changes during chemotherapy in patients with different pathological types of mammary cancer (MC)." (PMID 31700821, 2019). "Approximately 70% of breast cancers arising in BRCA1 mutation carriers and up to 23% of breast cancers in BRCA2 carriers display a triple negative phenotype." (PMID 30975216, 2019). "The proportion of BRCA1- and BRCA2-deficient breast cancers was also significantly higher in WSI compared to TCGA." (PMID 31022191, 2019). "As the lifetime risk of breast cancer is high, many women with PVs in BRCA1 or BRCA2 undergo risk-reducing mastectomy, which reduces the risk of breast cancer by 90–95%." (PMID 30832243, 2019). "Prophylactic oophorectomy in premenopausal women with BRCA2 pathogenic variants also has been shown to reduce the risk of breast cancer by approximately 50%." (PMID 31342359, 2019). "BRCA1 and BRCA2 gene mutations, confirmed to be linked to breast cancer in families, confer a 3.8- and 8.6-fold increased risk of developing prostate cancer, respectively." (PMID 31477094, 2019). "More than 1,800 distinct BRCA1 and 2,000 BRCA2 mutations have been reported in the Breast Cancer Information Core (BIC) database." (PMID 31131559, 2019). "PARP inhibitors, such as olaparib, are effective for the treatment of ovarian and breast cancers with deleterious BRCA1 or BRCA2 mutations." (PMID 31699977, 2019). "Despite PALB2 variants are rarely identified in 1–4% of BRCA negative families, but increasing evidence suggests its increased risk for breast cancer as compared to BRCA2 mutations." (PMID 30975222, 2019). "According to a Dutch study, the overall 10-year contralateral breast cancer risk for unselected BRCA1 or BRCA2 mutation carriers is approximately 18%, whereas that for mutation carriers with a family history of breast cancer is higher, at 25%." (PMID 30980249, 2019). "One of the mutated genes, BRCA2, is a well-known hereditary breast cancer gene that encodes a protein related to DNA damage repair during homologous recombination." (PMID 30760827, 2019).
breast cancer (continued). "This study utilizing only the direct sequencing methodology of BRCA1 gene and exon 11 of BRCA2 gene aimed to identify mutations that increase the familial susceptibility to breast cancer in families from different regions of Colombia." (PMID 31341521, 2019). "Apart from BRCA1 and BRCA2, the rarely mutated breast cancer predisposition genes PALB2 and FANCM have been associated with TNBC." (PMID 31683572, 2019). "These patients were selected because they were diagnosed with breast cancer between 1975 and 2015 and carried a BRCA2 mutation." (PMID 30723304, 2019). "BRCA1- and BRCA2-deficient breast cancers from WSI had 0.60 and 0.41 median proportion of signature 3 compared to median of 0 in BRCA-proficient breast cancers (P = 2.2 x 10−28 and 1.9 x 10−16, respectively)." (PMID 31022191, 2019). "The c.2808_2811delACAA pathogenic variant in BRCA2 was frequently reported in European populations, and was reported only once in a young black girl with breast cancer in Ibadan, Nigeria." (PMID 31060517, 2019). "High frequencies of mutations in BRCA1 and BRCA2 have already been observed in breast cancer patients of African ancestry from Nigeria and from the Bahamas." (PMID 30834239, 2019). "The BRCA2 is the most prevalent type mutation among breast cancer patients in the Arab region, with an estimated prevalence was 17% with a higher pooled prevalence of BRCA mutations in the Levant Region 28%." (PMID 30898109, 2019). "According to the estimates, about 10% of all ovarian cancer and 3%–5% of breast cancer cases are caused by mutations in the BRCA1 or BRCA2 genes." (PMID 31818005, 2019). "In this study, we investigated the features of genomic instability, expression of checkpoint molecules, and T cell-inflamed signature stratified by BRCA1- and BRCA2-deficiency status in two large series of breast cancer patients." (PMID 31022191, 2019). "The use of PARP (poly ADP ribose polymerase) inhibitor drugs for treating breast cancers or ovarian cancers with BRCA1/BRCA2 mutations is a widely documented example where synthetic lethality is used for effective treatment of cases with driver alterations." (PMID 31671773, 2019). "The BRCA1 or BRCA2 mutation detection rate in female breast cancer patients depends on factors such as age at diagnosis and breast cancer subtype." (PMID 31760547, 2019). "BRCA1 and BRCA2 germline mutation carriers have an increased risk of breast cancer, but the cellular and molecular basis of this increased risk is still poorly defined." (PMID 31519911, 2019). "It therefore seems unlikely that the presence of BRCA1/BRCA2 mutations is the reason for the raised breast cancer risks observed in this cohort." (PMID 30496607, 2019). "In our study, the patient of case 5, who had a BRCA2 mutation, presented with advanced breast cancer of nuclear grade 3 and a triple-negative subtype." (PMID 30980249, 2019). "Here, we report that BRCA1 and BRCA2-deficient breast cancers were associated with features of genomic instability including increased mutation burden." (PMID 31022191, 2019). "We report a novel pathogenic variant c.5219 T > G p.(Leu1740Ter) in BRCA2 in a consanguineous Senegalese family with a family history of breast cancer." (PMID 31060517, 2019). "BRCA1 and BRCA2 genes are the most commonly mutated genes that are associated with high breast cancer risk." (PMID 30975222, 2019). "In the current study, we report on the predictors of mortality, including ER status, in women with a BRCA2 mutation and breast cancer." (PMID 30723304, 2019).
breast cancer (continued). "Due to the strong association between BRCA mutations and early-onset breast carcinogenesis, genetic testing for BRCA1 and BRCA2 mutations has been suggested for individuals with breast cancer under the age of 60." (PMID 31775907, 2019). "There is definite evidence that prostate cancer risk is increased in BRCA1 and BRCA2 mutation carriers ascertained by a family history of breast cancer." (PMID 31477094, 2019). "The mean dose to the CB is especially important for patients younger than 40 yr old or with mutations in the breast cancer susceptibility gene, BRCA2, as they represent the population with higher risk for secondary breast cancers." (PMID 31183967, 2019). "Mono-allelic germline pathogenic variants in the Partner And Localizer of BRCA2 (PALB2) gene predispose to a high-risk of breast cancer development, consistent with the role of PALB2 in homologous recombination (HR) DNA repair." (PMID 31428676, 2019). "This suggests that different mechanisms of resistance to PARP inhibition must exist in these genetically distinct mouse models, with important clinical implications if such differences were replicated in BRCA1- and BRCA2-mutated human breast cancers." (PMID 31080552, 2019). "Patients with breast cancer who have a germline BRCA1/BRCA2 mutation are at increased risk of ipsilateral and contralateral tumours compared with those presenting with sporadic disease." (PMID 30689103, 2019). "Among high-risk genes for breast cancer BRCA2 (1.9% (23/1197)) and PALB2 (1.7% (20/1197)) had the highest VUS rates." (PMID 31159747, 2019). "In conclusion, we presented five cases of primary breast cancer in patients carrying a BRCA1 or BRCA2 mutation, whose tumors were diagnosed during surveillance." (PMID 30980249, 2019). "Women with a BRCA1 or BRCA2 pathogenic variant have a 50%‐80% risk of developing breast cancer and a 20%‐40% risk of developing ovarian cancer." (PMID 31531966, 2019). "Individuals with hereditary breast and ovarian cancer syndrome (HBOC), which is caused by germline pathogenic variants of BRCA1 or BRCA2, have an increased risk for breast cancer, ovarian cancer, prostate cancer, and pancreatic cancer." (PMID 31143373, 2019). "From the Korean Hereditary Breast Cancer study performed in Korea, one BRCA2 pathogenic variant (c.7480C>T) was identified as the Korean founder mutation using data from over 3,000 breast cancer patients." (PMID 31143373, 2019). "Germline mutations in BRCA1 and BRCA2 (BRCA1/2) genes are present in about 50% of cases of hereditary breast cancer." (PMID 31658756, 2019). "After adjustment for various prognostic factors and treatments, a BRCA2 mutation was associated with a significantly worse prognosis than a sporadic breast cancer (HR = 1.61; 95% CI 1.11–2.35, p = 0.01)." (PMID 30723304, 2019). "In this international cohort study of 390 breast cancer patients with a BRCA2 mutation, positive ER status was associated with a relatively poor prognosis compared to ER-negative status." (PMID 30723304, 2019). "It has been reported that frequency of LGRs ranges from approximately 6–27% of all detected BRCA1 pathogenic variants, and BRCA2 LGRs play a less role in hereditary breast cancer patients." (PMID 31174498, 2019). "Here, we report the functional characterization of the unclassified BRCA2 c.8299C > T variant, identified in a young breast cancer patient during BRCA1/2 NGS screening." (PMID 31569370, 2019). "Women at high‐risk for breast cancer include those with inherited mutations in the BRCA1 or BRCA2 genes and have a ~ 72 and ~ 69% lifetime risk of developing breast cancer by the age of 80, respectively." (PMID 31267556, 2019).